SHH (sonic hedgehog signaling molecule)
Diseases named in the same sentence as SHH in open-access papers (continued):
Sharing a sentence is not in itself a finding about the gene and the disease.
medulloblastoma (continued). "The two most well-defined subgroups are caused by overactive signaling in the WNT and SHH mitogenic pathways; less is understood about Groups 3 and 4 medulloblastoma." (PMID 24252460, 2013). "Constitutively, SHH-Gli signaling is active in basal cell carcinomas, medulloblastomas and cancers of esophagus, due to mutation in Patched or Smoothened." (PMID 22087285, 2011). "Hereditary loss of function mutations in the SHH receptor Patched (PTCH) lead to constitutive activation of the SHH pathway and predisposition to medulloblastoma in Gorlin syndrome." (PMID 19777070, 2009). "Some MYC-amplified medulloblastomas are associated with abnormal activation of SHH pathways." (PMID 39779613, 2025). "One prevalent subtype of medulloblastoma, a cerebellar brain tumor, is caused by the unrestricted proliferation of GCs with progenitor characteristics from aberrant activation of the SHH signaling pathway." (PMID 39137043, 2024). "Sixteen patients (57%) were considered standard-risk and 60% were SHH-activated medulloblastomas." (PMID 36920679, 2023). "Germline mutations in SUFU can also be seen in those harboring SHH-activated medulloblastoma." (PMID 37943476, 2023). "Disruption of the SHH pathway causes a range of well-characterized phenotypes, including holoprosencephaly, cerebellar hypoplasia, heart defects, skeletal abnormalities, and cancers such as medulloblastoma and basal cell carcinoma." (PMID 36995257, 2023). "Overall, these findings may help explain the differences in therapeutic outcomes in SHH-activated medulloblastomas and their susceptibility to targeted therapies." (PMID 37568705, 2023). "Adult SHH-activated medulloblastomas display a higher mutation burden compared to their pediatric counterparts, particularly with mutations associated with the SHH pathway, mainly Patched1 (PTCH1) and Smoothened (SMO), as well as mutations in CREB binding protein (CREBBP), BRPF1, and TERT promoter." (PMID 37568705, 2023). "However, only approximately 50% of SMOi-resistant medulloblastomas were shown to acquire mutations in the SHH pathway in a preclinical study, suggesting that additional mechanisms of resistance to SMOis must exist." (PMID 36688010, 2022). "Indeed, JQ1 decreases proliferation and viability of SHH-driven medulloblastoma cell lines in-vitro and in-vivo, even when mutations conferring these cell lines to SMO inhibitor resistance are present." (PMID 35745584, 2022). "In addition to the mutational landscape of SHH signaling components promoting medulloblastoma tumorigenesis, an interesting current topic is the contribution of SHH signaling to the initiation and progression of medulloblastoma." (PMID 34436033, 2021). "The developmental origins of medulloblastoma can be analyzed by pairing different Cre drivers with conditional mutations of the SHH receptor components Ptc and Smo directing SHH hyperactivation to broad lineages that include CGNPs or more narrow lineages within the CGNP population." (PMID 34021242, 2021). "However, when the subgroups are examined separately, WNT- and SHH-associated medulloblastomas have been shown to be more prevalent in females, demonstrating an uneven distribution of medulloblastoma subgroups according to sex." (PMID 33950317, 2021). "Moreover, we will discuss initial experiences in targeting new molecular alterations in gliomas (IDH mutations and NTRK fusions) and in medulloblastomas (SHH pathway)." (PMID 34360713, 2021). "At the same time, SJMB12 is investigating intensified treatment regimens for patients in higher risk subgroups, including the addition of gemcitabine and pemetrexed for those with high risk Group 3 or Group 4 medulloblastoma and targeted SHH inhibitor therapy for those with SHH-medulloblastoma." (PMID 34604027, 2021).
medulloblastoma (continued). "Interestingly, one of the cases (MB_2) was a rare SHH-activated medulloblastoma showing an IDH1:p.R132C mutation." (PMID 32758285, 2020). "We then compared the risk scores among established medulloblastoma molecular subgroups, including SHH, WNT, group 3, and group 4, as well as histology types, including classic, desmoplastic, LCA, and medulloblastoma with extensive nodularity (MBEN), using the GSE85217 dataset." (PMID 32508873, 2020). "Thus far, somatic mutation p.Leu923Pro has only been found in childhood medulloblastomas as the Sonic Hedgehog (SHH) pathway is likely involved in progression of these tumors." (PMID 32964316, 2020). "SHH medulloblastomas show unregulated ligand-independent SHH pathway signaling due to mutations/alterations such as loss-of-function of PATCHED (PTCH1) or Suppressor of Fused (SUFU), gain-of-function of Smoothened (SMO), GLI1, GLI2, or MYCN, and/or other alterations." (PMID 31554835, 2019). "A recent study showed that medulloblastomas can be subdivided into two prognostically different subgroups according to the G-protein alpha subunit Gsα (GNAS) levels: SHH-mutated GNAS-high tumors have a markedly better overall survival compared to SHH-mutated, GNAS-low tumors." (PMID 30279357, 2018). "In this study, we demonstrate that loss of AMPKα2 impairs SHH-driven medulloblastoma tumorigenesis." (PMID 30360486, 2018). "Medulloblastoma (MB) is the most common pediatric brain tumor, comprising four distinct molecular variants, one of which characterized by activation of the Sonic Hedgehog (SHH) pathway, driving 25–30% of sporadic MB." (PMID 29079783, 2017). "We efficiently induced bioluminescent medulloblastomas expressing eGFP-luciferase in BarTeL mice by infection of a limited number of somatic cGNPs with avian retroviral vectors encoding the active N-terminal fragment of SHH and a stabilized MYCN mutant." (PMID 27310018, 2016). "Also, Vismodegib- or NVP-LDE225- (SMO/SHH pathway inhibitors) resistant BCCs patients and mouse medulloblastoma cells have been shown to acquire mutations in SUFU or amplification of a downstream transcriptional effector of the SHH signaling pathway, GLI2." (PMID 27608848, 2016). "Most interestingly, neoplasms associated with mutations of the SHH pathway occur in areas where SHH is essential for the regulation of cellular stemness and differentiation such as in the cerebellum, the brain area where medulloblastomas emerge." (PMID 26266257, 2015). "The deregulation of the SHH signaling pathway in cerebellar granule neuron precursors is one of the crucial causes of the SHH subgroup of medulloblastoma, but recent observations also associate this signaling pathway with other central nervous system tumors, including gliomas." (PMID 26497896, 2015). "With respect to the interaction between Hippo and Sonic Hedgehog pathways, recent studies suggest that SHH signaling acts downstream of YAP in regulation of neuronal differentiation, being YAP either amplified or up-regulated in human SHH-associated medulloblastomas." (PMID 25607641, 2015). "Interestingly, medulloblastomas characterized by mutations in the SHH pathway tend to exhibit desmoplastic morphology." (PMID 19076778, 2009). "The SHH pathway was first implicated in medulloblastoma when germline mutations in the PTCH1 gene were found to be the cause of Gorlin's syndrome, a congenital condition characterized by increased incidence of basal‐cell carcinoma, medulloblastoma and rhabdomyosarcoma." (PMID 19076778, 2009).
medulloblastoma (continued). "Activation of the SHH signaling pathway in medulloblastoma can occur by mutations in PTCH1." (PMID 18769486, 2008). "The exact etiology and pathophysiology of medulloblastoma are poorly understood but are believed to involve genetic mutations and signaling pathway disruptions, particularly in the wingless-related integration, sonic hedgehog (SHH), and Group 3 and Group 4 pathways." (PMID 40958970, 2025). "Structural variations are frequent in pediatric solid tumors, particularly in osteosarcoma, adrenocortical carcinoma, H3K27M-mutated HGG, and Sonic hedgehog (SHH)-activated medulloblastoma, and may result from diverse mechanisms, including chromothripsis and chromoplexy." (PMID 38318504, 2023). "Hence, the treatment of mice harboring SMO-mutated SHH-activated medulloblastomas with PLX5622, an inhibitor of the colony-stimulating factor 1 receptor (CSF1R), resulted in a reduced proportion of TAMs in the tumor microenvironment, shrinkage in tumor sizes, and prolonged survival of the mice." (PMID 37568705, 2023). "However, ectopic expression of either human c-MYC or MYCN (mutationally stabilized and wild-type) in conjunction with SHH expression in Nestin-expression progenitor cells generated SHH medulloblastoma at a significantly increased incidence compared with infection with RCAS-SHH alone." (PMID 28333115, 2017). "In addition, combination of lithium with small-molecule inhibitors of the SHH pathway may represent an attractive regimen for high risk patients with SHH medulloblastoma." (PMID 25539912, 2014). "Medulloblastoma (MB) is the most frequent brain malignancy in children, frequently driven by deregulated Sonic Hedgehog (SHH) signaling." (PMID 42117983, 2026). "Combined inhibition of CMA and SHH pathway had a synergically therapeutic effect on SHH Medulloblastoma." (PMID 41797322, 2026). "DIPG, ATRT, and SHH-activated medulloblastoma tumors had an increase in leukocytes compared to normal brain based on PTPRC (CD45) expression." (PMID 41541220, 2026). "For example, lateral cerebellar hemispheric medulloblastomas usually belong to the sonic hedgehog (SHH) subgroup, whereas the location of posterior cranial fossa ependymomas and low-grade gliomas aids differentiating the (molecular) subgroups." (PMID 40892085, 2025). "Accordingly, in medulloblastoma cells, the SHH protein has been shown to upregulate EZH2, indicating that the Sonic Hedgehog pathway plays a role in the modulation of Polycomb proteins." (PMID 39971779, 2025). "SHH-medulloblastoma arises in Atoh1-expressing granule cell precursors (GCPs) on the surface of the developing cerebellum." (PMID 40766638, 2025). "In all three classifiers, for all infant cases, a sub-threshold class score indicated a tumor entity, usually SHH-activated medulloblastoma (5/6 samples by NCI-Bethesda, 6/6 by Epignostix, and 4/6 by CHLA classifier)." (PMID 40549014, 2025). "This alteration is particularly relevant in WNT and SHH subtypes of medulloblastoma, where hypermethylation of tumor suppressor genes correlates with poor prognosis and aggressive behavior." (PMID 40868156, 2025). "Among the most advanced clinical candidates is vismodegib, a Smoothened (SMO) inhibitor used in SHH-subtype medulloblastoma." (PMID 40868156, 2025). "Regarding medulloblastomas, 28 out of 29 (96.6%) tumours agreed with the initial diagnosis and were subclassified into Group 3 and Group 4 (7 tumours each, 25.0%), followed by SHH‐activated (8 tumours, 28.6%) and WNT‐activated (6 tumours, 21.4%)." (PMID 41033792, 2025).
medulloblastoma (continued). "Jude Children's Research Hospital confirmed activation of the SHH pathway and, by DNA methylation profiling identified a “methylation class medulloblastoma, group SHH, Subgroup 4” with high confidence (calibrated score = 0.99)." (PMID 40958970, 2025). "Among the 6 patients diagnosed with medulloblastoma, 4 patients were classified as sonic hedgehog (SHH)-activated tumors, and 2 patients were classified as group 4." (PMID 40351830, 2025). "In SHH-subtype medulloblastomas, histone methylation is crucial for maintaining SHH signaling pathways that support tumor growth and stemness." (PMID 40868156, 2025). "In medulloblastoma, it is reported that the total T cells are comparatively higher in sonic hedgehog (SHH) subgroup." (PMID 40575173, 2025). "These preclinical findings align with clinical observations, as patients with WNT-driven medulloblastoma typically exhibit superior survival outcomes compared to those with SHH-driven tumors under similar treatment regimens." (PMID 40948505, 2025). "Sonic hedgehog molecular group of medulloblastoma (SHH-MB) is a highly heterogeneous tumor entity, characterized by constitutive activation of the SHH signaling pathway." (PMID 40681754, 2025). "In contrast, the SHH subgroup accounts for approximately 30% of medulloblastoma cases and is characterized by the activation of the Sonic Hedgehog signaling pathway." (PMID 40868156, 2025). "Further refinement within these groups has identified subgroups such as SHH1–4 (within SHH-activated tumors) and subgroups 1–8 within Group 3/4 medulloblastomas." (PMID 40711574, 2025). "Of note, the proposed cell of origin for SHH-activated medulloblastoma is in the cerebellar granule neuron progenitor lineage." (PMID 40549014, 2025). "Recent studies have stratified medulloblastomas into a low-risk group with a good prognosis (wingless-type {WNT}, low-risk sonic hedgehog {SHH}, low-risk group 3/4) and a high-risk group with a poor prognosis (high-risk SHH, high-risk group 3/4)." (PMID 40291172, 2025). "SHH-activated tumors represent the most common medulloblastoma group among infant patients; however, the infant samples submitted in this study represent non-neoplastic, developmentally normal cerebellar cortex." (PMID 40549014, 2025). "Functional assays unveiled that EFTUD2 depletion in human medulloblastoma cells significantly curtailed cellular proliferation by impeding the activation of the SHH signaling pathway." (PMID 40275081, 2025). "There are a number of well-known driver genes for medulloblastoma, particularly SHH pathway genes in SHH medulloblastoma." (PMID 39753768, 2025). "Mutations in Sonic Hedgehog (SHH) signaling pathway genes, for example, Suppressor of Fused (SUFU), drive granule neuron precursors (GNP) to form medulloblastomas (MBSHH)." (PMID 39835775, 2025). "Sonic hedgehog subgroup of medulloblastoma (SHH-MB) is characterized by aberrant activation of the SHH signaling pathway." (PMID 39107797, 2024). "The development of medulloblastoma and basal cell carcinoma is largely driven by the Sonic Hedgehog (SHH) and Hippo pathways." (PMID 38233872, 2024). "In the cerebellum, SHH stimulates the proliferation of granule neuron precursors (GNPs) and the aberrant activation of the SHH signaling in these cells is responsible for medulloblastoma (MB) onset, the most common malignant pediatric brain tumor." (PMID 38062245, 2024).
medulloblastoma (continued). "Medulloblastomas frequently have either an activation of the wnt signalling pathway (wnt‐type of medulloblastoma) or a dysregulation of the sonic hedgehog (SHH) pathway." (PMID 39324445, 2024). "Inhibition of SHH signaling pathway by targeting Smoothened constitutes a potential therapeutic option for SHH-driven tumors including medulloblastoma." (PMID 39107797, 2024). "Further, AMP-activated kinase (AMPK) inactivation slows the progression of SHH-driven medulloblastoma." (PMID 38730706, 2024). "The mean 5-year OS and PFS were 65% (47–90%) and 62% (44–87%), respectively, in 22 patients with SHH-activated medulloblastoma." (PMID 39518048, 2024). "Upregulation of GLI1 of has previously been reported in sonic hedgehog (SHH) driven medulloblastoma and basal cell carcinoma (BCC)." (PMID 38307877, 2024). "Sonic Hedgehog (SHH) inhibitors vismodegib and glasdegib demonstrate activity against cerebellar stem cell-derived medulloblastoma CSCs exhibiting aberrant SHH pathway activation." (PMID 38800385, 2024). "Half of all medulloblastoma consisted of WNT-activated or SHH-activated groups, which can be diagnosed based on immunohistochemical stains." (PMID 38764578, 2024). "The analysis of 107 entries in the OMIM database using the keywords “medulloblastoma/+medulloblastoma” revealed pivotal stages in pathogenesis, notably the disruption of the SHH signaling pathway (OMIM 600725)." (PMID 39022728, 2024). "A further PCA performed on the tissue metabolite profiles from WNT, SHH, Group3 and Group4 medulloblastomas shows clustering by molecular group." (PMID 38184938, 2024). "In various cancer models—breast cancer cells, gastric cancer cells, medulloblastoma —CUR has been shown to inhibit the Hh pathway by downregulating the expression of SHh, PTCH1, and GLI1/GLI2." (PMID 39457084, 2024). "For instance, Sonic Hedgehog (SHH)-activated medulloblastomas are considered the most common subtype in adults, accounting for more than two-thirds of cases, while other subtypes are less frequent." (PMID 39518048, 2024). "Stabilization of GLI proteins by SUFU results in outsized SHH signaling responses, as manifested in altered limb development and medulloblastoma tumorigenesis." (PMID 38358805, 2024). "Sonic hedgehog (SHH) promotes proliferation of granule cell (GC) progenitors in the postnatal cerebellum and in the pediatric tumor, medulloblastoma, through specialized compartments called primary cilia." (PMID 39705308, 2024). "Last, in order to corroborate the translational potential of our findings, we assessed both monotherapies as well as their combination in human patient-derived xenograft organoids (PDXOs) representing SHH- and Group3-subgroup medulloblastoma." (PMID 39107797, 2024). "GAB1 immunostain was validated at AKUH at the conclusion of the study and is now routinely performed to enable identification of SHH-activated subtype of medulloblastoma." (PMID 38764578, 2024). "As multiple studies discussed in this review have shown, DDX3X is one of the most commonly recurring mutated genes in medulloblastoma cases, primarily seen in the WNT and SHH-subtypes of medulloblastoma." (PMID 39062517, 2024). "We obtained primarily diagnosed medulloblastoma (n = 170; 18 WNT, 46 SHH, 41 Group 3, and 65 Group 4) patient-specific mutations and transcriptome data from ICGC (PCAWG, Dec 2020)." (PMID 39160595, 2024). "Main occurrences in medulloblastoma include the formation of isochromosome 17q and SHH signaling pathway disruption." (PMID 39022728, 2024). "Human SHH-medulloblastoma tumors with higher REST expression exhibit nuclear localization of HIF1α, in contrast to its cytoplasmic localization in low-REST tumors." (PMID 38866867, 2024). "Rolipram and another PDE4 inhibitor, eggmanone, suppress SHH and Hedgehog signaling thereby inhibiting medulloblastoma growth in GNAS-mutant mice." (PMID 38233872, 2024).